ELOF1 (elongation factor 1)
Description:
Factor involved in transcription-coupled nucleotide excision repair (TC-NER), a mechanism that rapidly removes RNA polymerase II-blocking lesions from the transcribed strand of active genes. Acts as a key adapter required to anchor TC-NER factors to RNA polymerase II: stably positions UVSSA and the DCX(ERCC8) complex (also named CSA complex) on arrested RNA polymerase II, leading to neddylation and activation of the DCX(ERCC8) complex and ubiquitination of RNA polymerase II.
Synonyms: MGC4549; ELF1
Tractability: Small molecule: a structure with a bound ligand is known. PROTAC: ubiquitination databases record sites on it; its protein half-life has been measured.
Gene: Protein-coding gene on chromosome 19 (11,551,147 to 11,559,325, reverse strand). Ensembl gene ENSG00000130165.
Subcellular location: Nucleus; Chromosome
Subcellular location (Human Protein Atlas): Cytosol
Gene Ontology:
Molecular function: protein binding; protein-macromolecule adaptor activity; RNA polymerase II complex binding
Biological process: transcription-coupled nucleotide-excision repair
Cellular component: chromosome; nucleus; transcription elongation factor complex
Genetic constraint (gnomAD): Loss-of-function variants: 4 observed, 7.44 expected, observed/expected ratio (o/e) 0.54, 90% interval 0.26 to 1.23. That is too few expected variants to judge how well the gene tolerates losing a copy. Missense variants: 59 observed, 90.99 expected, observed/expected ratio (o/e) 0.65, 90% interval 0.52 to 0.81. Synonymous variants: 31 observed, 33.34 expected, observed/expected ratio (o/e) 0.93, 90% interval 0.7 to 1.25.
Homologues: Orthologues: guinea pig ELOF1 (100% identical), macaque ELOF1 (100% identical), mouse Elof1 (100% identical), rat Elof1 (100% identical), tropical clawed frog elof1 (96% identical), zebrafish elof1 (94% identical), chimpanzee ELOF1 (78% identical), dog ELOF1 (77% identical), Drosophila melanogaster CG40228 (71% identical), Caenorhabditis elegans elof-1 (69% identical).
Diseases named in the same sentence as ELOF1 in open-access papers:
ELOF1 is named in the same sentence as 10 diseases in open-access papers, as found by Europe PMC text mining. Sharing a sentence is not in itself a finding about the gene and the disease. The quoted sentences say what the papers report.
Cockayne syndrome (1 paper, 2024). A multisystem condition characterized by short stature, a characteristic facial appearance, premature aging, photosensitivity, progressive neurological dysfunction, and intellectual deficit. "Unlike the core TC-NER factors CSB, CRL4CSA, and UVSSA, mutations in which give rise to Cockayne syndrome and UV-sensitive syndrome, respectively, STK19 and ELOF1 have not yet been linked to these human disorders." (PMID 39547228, 2024).
colorectal cancer (1 paper, 2022). A primary or metastatic malignant neoplasm that affects the colon or rectum. "We performed a colony formation assay to directly assessthe growth inhibitory effect of P5091, XL177A, and ELOF1 KO in bothSW480-APC-mutant colorectal cancer cells and normalcolorectal cells." (PMID 36589880, 2022).
ovarian carcinoma (1 paper, 2021). A malignant neoplasm originating from the surface ovarian epithelium. "EEF1A2 encodes an isoform of the alpha subunit of the elongation factor-1 complex and may be critical in the development of ovarian cancer." (PMID 34220510, 2021).
infection (1 paper, 2024). The state of being infected such as from the introduction of a foreign agent such as serum, vaccine, antigenic substance or organism. "The successful infection was verified with the expression, and the accumulation of the protein synthesis elongation factor 1 gene, PsEF1, belonging to Pst was verified with consistency across two biological replicates." (PMID 38611510, 2024).
ELOF1 also shares sentences with these, for which no sentence is quoted: Allergy (1 paper); carcinoma (1); Fibroadenoma (1); tumor (1); UV-sensitive syndrome (1); visceral leishmaniasis (1).